MOXD1 (monooxygenase DBH like 1)
Synonyms: MOX; DKFZP564G202; dJ248E1.1; PRO5780
Tractability: Antibody: UniProt predicts a signal peptide or a membrane-spanning region. PROTAC: ubiquitination databases record sites on it.
Gene: Protein-coding gene on chromosome 6 (132,296,055 to 132,401,556, reverse strand). Ensembl gene ENSG00000079931.
Subcellular location: Endoplasmic reticulum membrane
Subcellular location (Human Protein Atlas): Cytosol
Gene Ontology:
Molecular function: protein binding; oxidoreductase activity, acting on paired donors, with incorporation or reduction of molecular oxygen, reduced ascorbate as one donor, and incorporation of one atom of oxygen; catalytic activity; copper ion binding; dopamine beta-monooxygenase activity; monooxygenase activity
Cellular component: endoplasmic reticulum membrane; secretory granule membrane
Genetic constraint (gnomAD): Loss-of-function variants: 55 observed, 61.45 expected, observed/expected ratio (o/e) 0.9, 90% interval 0.72 to 1.12. The upper end of that interval is the gene's LOEUF score, 1.12, which puts it in group 4 of 6, group 1 being the genes least tolerant of losing a copy. Missense variants: 830 observed, 735.42 expected, observed/expected ratio (o/e) 1.13, 90% interval 1.07 to 1.2. Synonymous variants: 298 observed, 270.75 expected, observed/expected ratio (o/e) 1.1, 90% interval 1 to 1.21.
Homologues: Orthologues: chimpanzee MOXD1 (99% identical), macaque MOXD1 (98% identical), pig MOXD1 (91% identical), guinea pig MOXD1 (87% identical), mouse Moxd1 (85% identical), rat Moxd1 (85% identical), rabbit MOXD1 (82% identical), tropical clawed frog moxd1 (63% identical), zebrafish moxd1 (59% identical), Drosophila melanogaster olf413 (32% identical), Drosophila melanogaster CG5235 (30% identical). Paralogues in human: DBH (31% identical).
Diseases named in the same sentence as MOXD1 in open-access papers:
MOXD1 is named in the same sentence as 30 diseases in open-access papers, as found by Europe PMC text mining. Sharing a sentence is not in itself a finding about the gene and the disease. The quoted sentences say what the papers report.
glioblastoma (5 papers, 2022 to 2025). The most malignant astrocytic tumor (WHO grade IV). "Expression of Moxd1 is also associated with poor survival in glioblastoma, whilst when it is downregulated, it activates ER-stress causing activation of the unfolded protein response." (PMID 36980965, 2023). "A recent study on glioblastoma, a tumor form derived from neural crest derivatives other than the trunk, i.e., with a separate origin from neuroblastoma, identified that high MOXD1 expression is associated with a poor prognosis, opposite to our findings in neuroblastoma." (PMID 38905335, 2024). "MOXD1 knockdown induced endoplasmic reticulum (ER) stress, triggering the ER‒mitochondrial apoptosis pathway and modulating the progression of glioblastoma (GBM)." (PMID 40989158, 2025). "MOXD1 has also been predicted to enable copper ion–binding activity, and MOXD1 knockdown significantly suppresses the proliferation and tumor growth of glioblastoma cells via ER stress-inducing apoptosis." (PMID 36045691, 2022). "However, it is not understandable that the biological function and molecular mechanism of MOXD1 in Glioblastoma (GBM)." (PMID 35393406, 2022).
gastric cancer (3 papers, 2024 to 2025). A primary or metastatic malignant neoplasm involving the stomach. "This study demonstrated that heightened MOXD1 expression is associated with decreased overall survival rates in patients with gastric cancer." (PMID 38200441, 2024). "In gastric cancer, FTO silencing reduces the expression of MOXD1, a gene associated with poor prognosis, and may influence cancer‐related pathways." (PMID 41141648, 2025). "In addition, MOXD1 expression was one of the biomarkers of early gastric cancer." (PMID 38200441, 2024).
bladder cancer (2 papers, 2022 to 2025). "In bladder cancer, MOXD1 was found to be associated with copper metabolism." (PMID 40989158, 2025). "To further verify the localization of MOXD1 in fibroblasts in bladder cancer tissue, we explored the correlation of MOXD1 expression with fibroblasts in the TIMER 2.0 database." (PMID 36620542, 2022). "Additionally, MOXD1 is a potentially important prognostic biomarker in bladder cancer, high-grade serous ovarian cancer (HGSOC), and hepatocellular carcinoma." (PMID 40989158, 2025). "Based on further exploration through single-cell analysis, we also found that MOXD1 is mainly overexpressed in fibroblasts, suggesting that fibroblasts may play an important role in shaping the immune microenvironment in bladder cancer by changing the transport and activity of copper ions." (PMID 36620542, 2022). "We then attempted to explore the localization of MOXD1 in the tumor microenvironment and its specific impact on the tumor immune microenvironment (TIM) by analyzing the single-cell analysis expression profiles of bladder cancer in the GSE135337 dataset." (PMID 36620542, 2022).
diabetic kidney disease (2 papers, 2023 to 2025). Progressive kidney disorder caused by vascular damage to the glomerular capillaries, in patients with diabetes mellitus. "In chronic obstructive pulmonary disease and diabetic kidney disease, MOXD1 expression was found to be associated with disease occurrence, providing indirect evidence that MOXD1 plays a role in chronic inflammation." (PMID 40989158, 2025).
osteosarcoma (2 papers, 2021 to 2024). A usually aggressive malignant bone-forming mesenchymal neoplasm, predominantly affecting adolescents and young adults. "Suppression of MOXD1 through knockdown techniques was observed to hinder the proliferation of osteosarcoma cells and impede growth of xenograft tumors by inducing apoptosis." (PMID 38200441, 2024). "MOXD1 belongs to the copper-dependent monooxygenase family, whose knockdown would suppress the proliferation of osteosarcoma cells via inducing apoptosis." (PMID 33878734, 2021).
skin aging (2 papers, 2022 to 2023). The gradual irreversible changes in structure of skin that occur as a result of the passage of time.. "Then, we confirmed the down-regulated expressions of ABCC4, PTGER3, BCEH, HPGD, and MOXD1 in normal group, while AR, CXCR2, HSD17B2, ODC1, PI3, PLAU and THBS2 were up-regulated in skin aging group." (PMID 37310405, 2023).
bladder tumors (1 paper, 2022). "The results indicated that the MOXD1 expression level of samples in the Rose cohort increased as the risk of death from bladder tumors decreased, consistent with the results obtained using the IMvigor210 cohort." (PMID 36620542, 2022).
colon cancer (1 paper, 2024). "To explore the prognostic role of MOXD1 across cancer types of an origin separate from neural crest, we analyzed patient data from patients with breast and colon cancer." (PMID 38905335, 2024).
epilepsy (1 paper, 2022). A brain disorder characterized by episodes of abnormally increased neuronal discharge resulting in transient episodes of sensory or motor neurological dysfunction, or psychic dysfunction. "To date, MOXD1 has not been directly associated with epilepsy, thus, the existence of a role in determining a phenotype such as ADSHE could not be inferred." (PMID 36231847, 2022).
Hernia (1 paper, 2021). "Among these, nine genes (CD2, GPT2, MOXD1, ENSSSCG00000031037, ENSSSCG00000032582, ENSSSCG00000036224, ENSSSCG00000036983, ENSSSCG00000037009 and ENSSSCG00000039111) had different expression profiles when comparing both types of hernia." (PMID 33513662, 2021).
liver disease (1 paper, 2023). "Altogether, our data indicate that NTBC therapy does not completely resolves HT1-driven liver disease and supports the sustained risk to develop HCC over time as different HCC markers, including Moxd1, Saa, Mt, Dbp and Cxcl1, were significantly increased under NTBC." (PMID 36980965, 2023).
lymph node metastasis (1 paper, 2025). "Moreover, high MOXD1 expression was found to promote lymph node metastasis in GC patients." (PMID 40989158, 2025).
melanoma (1 paper, 2024). A malignant, usually aggressive tumor composed of atypical, neoplastic melanocytes. "We found that the MOXD1 expression is higher in melanomas than in neuroblastomas and that the MOXD1 levels are slightly higher in metastatic than in primary melanomas." (PMID 38905335, 2024). "Comparing neuroblastoma to malignant melanoma using data from the Cancer Cell Line Encyclopedia cohort showed that the MOXD1 expression was significantly lower in neuroblastoma." (PMID 38905335, 2024). "Given our findings on MOXD1 in neuroblastoma, we evaluated expression of MOXD1 in melanoma, which, like neuroblastoma, originates from trunk neural crest cells." (PMID 38905335, 2024).
neuroblastoma (1 paper, 2024). Neuroblastoma (NB) is the most common solid, extracranial childhood tumor. "Together, this demonstrates that the low expression or loss of MOXD1 is correlated with unfavorable disease in neuroblastoma." (PMID 38905335, 2024). "Herein, we analyzed RNA sequencing data obtained from human neuroblastoma samples and found that loss of expression of trunk neural crest–enriched gene MOXD1 associates with advanced disease and worse outcome." (PMID 38905335, 2024). "Herein, we identified MOXD1 as a de novo tumor-suppressor gene in neuroblastoma, effective by loss of the 6q23 locus surrounding this gene." (PMID 38905335, 2024). "Next, we evaluated a subset of individuals with neuroblastoma for possible causes of low MOXD1 expression and found altered copy number profile, suggesting the presence of chromosomal losses surrounding the MOXD1 locus (6q23.2, fig." (PMID 38905335, 2024). "We found that low expression level of MOXD1 is an independent prognostic marker of poor outcome among patients with neuroblastoma of all stages and risk groups." (PMID 38905335, 2024). "For example, identification of affected signal transduction, chromatin remodeling, or ion exchange, could open up new avenues for targeting neuroblastomas caused by loss of MOXD1." (PMID 38905335, 2024). "In addition, individuals with loss of function of MOXD1 had reduced survival rates compared to the rest of the cohort of neuroblastoma patients with high-risk disease, which already have a dismal prognosis." (PMID 38905335, 2024). "To evaluate the sufficiency of loss of MOXD1 to drive neuroblastomas, we knocked out MOXD1 with CRISPR-Cas9 in the MES-dominant SH-EP cells that express high endogenous levels of MOXD1." (PMID 38905335, 2024). "Our knockout and overexpression studies support that MOXD1 acts as a tumor-suppressor gene in neuroblastoma." (PMID 38905335, 2024). "The overexpression of MOXD1 showed delay in tumor growth and increase in animal survival in three different neuroblastoma cell models." (PMID 38905335, 2024). "Together, the results show that low expression of the trunk neural crest–enriched gene MOXD1 is an independent prognostic marker of poor outcome in neuroblastoma." (PMID 38905335, 2024). "MOXD1 is a tumor-suppressor gene and a lineage-specific marker for immature and mesenchymal cells in neuroblastoma." (PMID 38905335, 2024). "Together, these results demonstrate that expression of MOXD1 suppresses neuroblastoma tumorigenesis." (PMID 38905335, 2024). "Further, by using single-cell RNA sequencing data of human neuroblastoma cells and fetal adrenal glands and creating in vivo models of zebrafish, chick, and mouse, we show that MOXD1 is a determinate of tumor development." (PMID 38905335, 2024). "Our findings identify MOXD1 as a lineage-restricted tumor-suppressor gene in neuroblastoma, potentiating further stratification of these tumors and development of novel therapeutic interventions." (PMID 38905335, 2024). "To further demonstrate the tumor-suppressing capacity of MOXD1, we set up the opposite experiment, i.e., overexpressed the protein in neuroblastoma cells that completely lack endogenous expression." (PMID 38905335, 2024). "In addition, we found that MOXD1 expression is highly conserved and restricted to mesenchymal neuroblastoma cells and Schwann cell precursors during healthy development." (PMID 38905335, 2024). "This hypothesis was supported by our observation that MOXD1 is expressed almost exclusively in SCPs, a subpopulation with a gene expression signature score correlating with a more favorable prognosis in neuroblastoma." (PMID 38905335, 2024). "In conclusion, we found that MOXD1 is a tumor-suppressor gene in neuroblastoma." (PMID 38905335, 2024). "We evaluated whether low MOXD1 expression is specific to neuroblastomas by analyzing data from multiple other neural crest–derived and nonneural crest–derived cancers." (PMID 38905335, 2024).
neuroblastoma (continued). "Next, we detected that MOXD1, as well as the MES-associated PRRX1, SNAI2, and NOTCH2 genes were virtually restricted to the MES-like SH-EP cells by analyzing extracted RNA from five different conventional neuroblastoma cell lines." (PMID 38905335, 2024). "Thus, herein, we used these translational models to evaluate the impact of altered MOXD1 expression on neuroblastoma formation together with combined data obtained from correlative single-cell studies and patient tumor material." (PMID 38905335, 2024). "Expression of CD44 was high in cells in which we overexpressed MOXD1, which is consistent with the previous finding that CD44 is expressed in undifferentiated multipotent neural crest cells and has been shown to be associated with favorable prognosis in neuroblastoma." (PMID 38905335, 2024). "In line with this, MOXD1 expression was restricted to SCPs during normal development of human and mouse adrenal medulla, reflecting the overlap between normal SCPs and MES neuroblastoma cell phenotypes, which was previously reported." (PMID 38905335, 2024). "The neuroblastoma MES gene signature has previously been shown to have pronounced overlap with the SCP cluster, further emphasizing the corresponding lineage-specific expression of MOXD1 in both healthy and tumor development." (PMID 38905335, 2024).
pulmonary fibrosis (1 paper, 2023). Chronic progressive interstitial lung disorder characterized by the replacement of the lung tissue by connective tissue, leading to progressive dyspnea, respiratory failure, or right heart failure. "MOXD1 is a copper-binding protein and copper itself has been implicated in pulmonary fibrosis." (PMID 37085855, 2023). "Furthermore, we find that MOXD1 is also expressed at early stages of IPF suggesting that it can be used as an early biomarker of fibroblast pulmonary fibrosis." (PMID 37085855, 2023).
tumor (9 papers, 2021 to 2025). "If loss of MOXD1 is caused by altered lineage commitment, it will be of importance to understand how this is regulated at a mechanistic level, and the impact it potentially has on tumor initiation and progression." (PMID 38905335, 2024). "Recently, scRNA-Seq analyses performed on nodular and diffuse pNFs revealed the presence of CAFs (Fb population transiently present in dyNFs) and of tumor SC expressing dyNF markers (Moxd1 and Uchl1) only in nodular NFs (unpublished results)." (PMID 41223283, 2025). "The mRNA expression of MOXD1 in tumor tissue was significantly greater than that in adjacent normal tissue." (PMID 40989158, 2025). "In the present study, MOXD1 mRNA expression levels in tumor tissue samples from the training cohort were significantly increased (compared with those in the corresponding para-tumorous normal tissue samples)." (PMID 40989158, 2025). "We found that MOXD1 knockout during the embryonic stage increased the tumor penetrance to 100% (n = 21 of 21)." (PMID 38905335, 2024). "Our RNA-seq data indeed identified ion transport as one of the most affected processes connected to MOXD1, and, notably, we found that the copper ion–binding protein APOA4 is up-regulated with MOXD1 overexpression in tumor cells." (PMID 38905335, 2024). "We indeed found that MOXD1 knockout increased tumor penetrance, tumor formation, and cell motility, leading to more aggressive disease." (PMID 38905335, 2024). "As visualized before tumor dissection, the MOXD1 knockout cells were also more migratory (tumor and motile cells marked by dashed lines)." (PMID 38905335, 2024). "The results demonstrated that under the TIDE, XCELL, EPIC, and MCPCOUNTER algorithms, MOXD1 expression was positively correlated with tumor infiltration by fibroblasts." (PMID 36620542, 2022). "QRT-PCR showed that the expression of the DRAXIN, ITPRID2, and MAP3K1 were significantly upregulated while MOXD1 was downregulated in tumor samples." (PMID 36045691, 2022). "Monooxygenase DBH-like 1 (MOXD1) was further identifified, and its potential for evaluating the tumor immune microenvironment and predicting the immunotherapy response was explored." (PMID 36620542, 2022). "In GBM, MOXD1 knockdown inhibited the proliferation, migration, and invasion of GBM cells and triggered apoptosis in ER-associated mitochondria, ultimately impacting tumor progression." (PMID 40989158, 2025). "Further research is needed to determine whether MOXD1 regulates OS levels in the tumor microenvironment." (PMID 40989158, 2025). "Therefore, MOXD1 expression (at the transcriptome level) increases with tumor progression and metastasis." (PMID 40989158, 2025). "In addition, patients with high MOXD1 mRNA expression exhibited high infiltration of NK cells, which are known to play a key role in tumor cell killing." (PMID 40989158, 2025). "Patients with high MOXD1 mRNA expression also presented lower tumor purity and higher TIDE scores." (PMID 40989158, 2025). "Indeed, the immune response in patients with high MOXD1 mRNA expression levels was significantly greater than that in patients with low MOXD1 mRNA expression levels, and these patients also presented lower tumor purity." (PMID 40989158, 2025). "MOXD1 expression was higher in Primary tumor group than Normal group." (PMID 38200441, 2024). "Notably, all surviving mice in the 691-ADRN MOXD1 overexpressing (MOXD1 OE) group were tumor free at the experimental end point (365 days) as compared to the CTRL group in which all mice had tumors." (PMID 38905335, 2024). "MOXD1 expression was increased in STAD tumor and STAD stage II, III, and IV compared with Stage I." (PMID 38200441, 2024). "In addition, we further screened the MOXD1 gene as a key node affecting the relationship between copper related genes and immune characteristics in tumor tissues of BLCA patients." (PMID 36620542, 2022).